SLC25A38 (solute carrier family 25 member 38)
Description:
Mitochondrial glycine transporter that imports glycine into the mitochondrial matrix. Plays an important role in providing glycine for the first enzymatic step in heme biosynthesis, the condensation of glycine with succinyl-CoA to produce 5-aminolevulinate (ALA) in the mitochondrial matrix. Required during erythropoiesis. Plays a role as pro-apoptotic protein that induces caspase-dependent apoptosis.
Synonyms: FLJ20551; SIDBA2
Tractability: Antibody: UniProt predicts a signal peptide or a membrane-spanning region. PROTAC: its protein half-life has been measured.
Gene: Protein-coding gene on chromosome 3 (39,383,347 to 39,397,351, forward strand). Ensembl gene ENSG00000144659.
Subcellular location: Mitochondrion inner membrane
Gene Ontology:
Molecular function: glycine transmembrane transporter activity
Biological process: erythrocyte differentiation; glycine import into mitochondrion; heme biosynthetic process
Cellular component: mitochondrion; mitochondrial inner membrane; membrane
Genetic constraint (gnomAD): Loss-of-function variants: 27 observed, 35.36 expected, observed/expected ratio (o/e) 0.76, 90% interval 0.56 to 1.05. The upper end of that interval is the gene's LOEUF score, 1.05, which puts it in group 4 of 6, group 1 being the genes least tolerant of losing a copy. Missense variants: 344 observed, 406.44 expected, observed/expected ratio (o/e) 0.85, 90% interval 0.77 to 0.93. Synonymous variants: 123 observed, 153.98 expected, observed/expected ratio (o/e) 0.8, 90% interval 0.69 to 0.93.
Homologues: Orthologues: chimpanzee SLC25A38 (100% identical), macaque SLC25A38 (99% identical), dog SLC25A38 (91% identical), pig SLC25A38 (90% identical), guinea pig SLC25A38 (88% identical), mouse Slc25a38 (87% identical), rat Slc25a38 (84% identical), rabbit SLC25A38 (78% identical), tropical clawed frog slc25a38 (64% identical), zebrafish slc25a38b (57% identical), zebrafish slc25a38a (56% identical). Paralogues in human: SLC25A23 (27% identical), SLC25A12 (27% identical), SLC25A13 (26% identical), SLC25A24 (25% identical), SLC25A30 (25% identical), SLC25A1 (25% identical), SLC25A14 (25% identical), SLC25A45 (25% identical), SLC25A37 (25% identical), UCP1 (25% identical), SLC25A48 (24% identical), UCP2 (24% identical), and 37 more.
Diseases named in the same sentence as SLC25A38 in open-access papers:
SLC25A38 is named in the same sentence as 22 diseases in open-access papers, as found by Europe PMC text mining. Sharing a sentence is not in itself a finding about the gene and the disease. The quoted sentences say what the papers report.
congenital sideroblastic anemia (10 papers, 2014 to 2025). "The second most common non-syndromic congenital sideroblastic anemia is due to mutations in the SLC25A38 gene." (PMID 35885655, 2022). "A common subtype of congenital sideroblastic anemia is due to autosomal recessive mutations in the SLC25A38 gene." (PMID 26821380, 2016). "Solute carrier family 25 member 38 (SLC25A38) was recently identified through the positional cloning of a gene implicated in nonsyndromic congenital sideroblastic anemia." (PMID 26557657, 2015). "According to recent human genetics findings, mutations in FECH, ALAS2, and CLPX underlie most cases of the disorder erythropoietic protoporphyria, while mutations in ALAS2 and in the mitochondrial glycine transporter SLC25A38 are the most frequent causes of congenital sideroblastic anemia." (PMID 38927630, 2024). "Mutations in the human SLC25A38 gene cause congenital sideroblastic anemia." (PMID 28404662, 2017). "SLC25A38 gene has been previously linked to congenital sideroblastic anemia." (PMID 25955609, 2015). "The current treatment for SLC25A38 congenital sideroblastic anemia is chronic blood transfusion coupled with iron chelation." (PMID 26821380, 2016). "Given the tolerability of glycine and folate in humans, this study points to a potential novel treatment for SLC25A38 congenital sideroblastic anemia." (PMID 26821380, 2016). "Mutations in several genes cause congenital sideroblastic anemia (CSA) including ALAS2, SLC25A38, ABCB7, GLRX5, SLC19A2, PUS1, and YAR2." (PMID 26821380, 2016). "Mutations in the SLC25A38 gene are responsible for the second most common form of congenital sideroblastic anemia (CSA), a severe condition for which no effective treatment exists." (PMID 39769087, 2024). "Using this new knowledge, we go on to determine that supplementation with glycine and folate restore hemoglobin levels in a zebrafish model of the disease pointing to a potentially new, safe, and cost effective treatment for SLC25A38 congenital sideroblastic anemia." (PMID 26821380, 2016). "SLC25A38 belongs to the SLC25 family and previous studies have found that variations in the SLC25A38 gene, which is located on chromosome 3p22, are responsible for severe pyridoxine-refractory congenital sideroblastic anemia." (PMID 24765149, 2014). "While neither glycine nor 5-Ala could ameliorate SLC25A38 congenital sideroblastic anemia in a zebrafish model, we determined that the addition of folate with glycine was able to restore hemoglobin levels." (PMID 26821380, 2016).
sideroblastic anemia (9 papers, 2013 to 2024). "In fact, the responsiveness to pyridoxine seen in XLSA also helps to distinguish it from other congenital causes of inherited sideroblastic anemia with mutations in SLC25A38, ABCB7, GLRX5, PUS1, and SLC19A genes." (PMID 39995829, 2024). "While sideroblastic anemia seems to be the primary phenotypic defect associated with SLC25A38 mutations, these patients often have other disorders." (PMID 35832791, 2022). "The case of an infant girl with severe congenital sideroblastic anemia associated with a novel molecular defect in mitochondrial transporter SLC25A38 is presented." (PMID 30214775, 2018). "Of three cases diagnosed by referring physicians as sideroblastic anaemia, one (P33) was homozygous for a mutation in SLC25A38 predicted to be pathogenic due to a frameshift leading to an early termination codon consistent with the bone marrow findings." (PMID 27432187, 2016). "Defects in δ–Alas2, Abcb7 [ATP-binding cassette, sub-family B (MDR/TAP), member 7], Glrx5 [glutaredoxin 5 homolog (S. cerevisiae)] and Slc25a38 (solute carrier family 25, member 38) are causal to different forms of sideroblastic anemias." (PMID 24124461, 2013). "Congenital sideroblastic anemias are caused by defects in the early steps in heme synthesis, including those encoding the human homologs of yeast HEM25 (SLC25A38 in humans) and HEM1 (ALAS2 in humans)." (PMID 28404662, 2017). "We found that the addition of glycine plus folate substantially increased hemoglobin level in the zebrafish SLC25A38 congenital sideroblastic anemia model." (PMID 26821380, 2016).
anemia (4 papers, 2015 to 2024). A reduction in the number of red blood cells, the amount of hemoglobin, and/or the volume of packed red blood cells. "Our findings reveal a distinct differential expression profile in the SLC25A38 patient compared to other congenital anemia groups." (PMID 39519257, 2024). "The role of SLC25A38 in anemia has been widely reported, but its role in cancer has rarely been studied." (PMID 35411037, 2022). "Moreover, we observed a unique gene profile in the SLC25A38 patient with respect to other congenital anemia groups." (PMID 39519257, 2024). "Patients with CSA caused by SLC25A38 mutation commonly exhibit early onset, no gender differences, severe microcytic-hypochromic anemia, and are nonsyndromic." (PMID 25985931, 2015).
acute lymphoblastic leukemia (2 papers, 2014 to 2024). Leukemia with an acute onset, characterized by the presence of lymphoblasts in the bone marrow and the peripheral blood. "In fact, SLC25A38 is upregulated in about half of acute lymphoblastic leukemia (ALL) patients and in cell lines such as RPMI 8226, U266, Molt-4, and Jurkat." (PMID 39795950, 2024). "In order to clarify the effect of SLC25A38 protein expression on acute lymphoblastic leukemia (ALL) cells, we detected the expression of SLC25A38 in various cell lines (RPMI 8226, U266, Molt-4 and Jurkat) by western blot analysis." (PMID 24765149, 2014).
hepatocellular carcinoma (2 papers, 2021 to 2022). A malignant tumor that arises from hepatocytes. "But, decreased expression of SLC25A38 was found in hepatocellular carcinoma and associated with microvascular invasion." (PMID 34434692, 2021). "Glycine plays a role in iron metabolism, which is crucial to hepatocellular carcinoma progression, thus, representative iron utilization genes including SLC25A38 were investigated." (PMID 35411037, 2022). "However, SLC25A38 does not affect the prognosis of hepatocellular carcinoma patients." (PMID 35411037, 2022).
leukemia (2 papers, 2014 to 2017). A malignant (clonal) hematologic disorder, involving hematopoietic stem cells and characterized by the presence of primitive or atypical myeloid or lymphoid cells in the bone marrow and the blood. "Therefore, we hypothesized that the SLC25A38 protein may be significant in the pathological changes associated with leukemia." (PMID 24765149, 2014). "Among 55 leukemia patients (adult, n=32 and infant, n=23), a high expression of SLC25A38 protein was observed in seven infant (7/23, 30.4%) and 15 adult (15/32, 46.9%) ALL patients." (PMID 24765149, 2014). "The expression of SLC25A38 protein was detected in the 55 leukemia patients and the results showed that a high expression of SLC25A38 was common in adult (15/32, 46.9%) and infant (7/23, 30.4%) ALL patients." (PMID 24765149, 2014). "Western blot analysis was used to analyze the expression of SLC25A38 protein in various MM and leukemia cell lines." (PMID 24765149, 2014). "The data indicates that future studies are required to determine the role of SLC25A38 in the pathogenesis of leukemia, and establish whether overexpression of this protein regulates the proliferation, differentiation and apoptosis of leukemia cells." (PMID 24765149, 2014). "Moreover, UCK1, SLC25A38, VDAC1 in our signature have been reported to be involved in proliferation or apoptosis of leukemia cell lines." (PMID 27903973, 2017).
bone marrow failure (1 paper, 2024). "We observed clear differential expression patterns between patients with congenital hemolytic anemia (thalassemia and SCD) and congenital anemia due to bone marrow failure (CSA with the SLC25A38 mutation) and then compared them to healthy controls." (PMID 39519257, 2024).
endometrial cancer (1 paper, 2023). Primary or metastatic malignant neoplasm involving the endometrium (mucous membrane that lines the endometrial cavity). "Further analysis showed that estrogen and succinate increased the expression of ALAS1 and SLC25A38 in uterine endometrial cancer cells (UECC), and the administration of succinate upregulated the level of the estrogen receptor (ER)." (PMID 37509133, 2023).
erythroleukemia (1 paper, 2024). Acute erythroid leukemia characterised by the presence of at least 50% erythroid precursors and at least 20% myeloblasts in the bone marrow. "We developed and characterized a K562 erythroleukemia cell line with markedly reduced expression of the SLC25A38 protein (A38-low cells)." (PMID 39769087, 2024).
iron overload (1 paper, 2015). "Patients with mutations in SLC25A38 had severe microcytic-hypochromic anemia and systemic iron overload very early in life." (PMID 25985931, 2015).
metastatic tumors (1 paper, 2022). "The mutation of BAP1 was previously reported to be associated with the UM metastasis, but only 50% (13/26) of metastatic tumors presented with BAP1 mutation, whose incidence was also much lower than that of SLC25A38 downregulation." (PMID 35411037, 2022). "Further analyses showed that metastatic cases tended to have lower SLC25A38 expression and higher levels of molecules involving in cell proliferation, cell adhesion, cell motility, and angiogenesis compared to non-metastatic tumors in both TCGA cohort and GSE22138 cohort." (PMID 35411037, 2022).
microcytic anemia (1 paper, 2013). Anemia in which the red blood cell volume is decreased. "Therefore, CSA patients with microcytic anemia, in whom mutations of ALAS2 gene were not identified, were expected to harbor SLC25A38 mutation; however, it was not detectable in this study." (PMID 22983749, 2013).
viral infection (1 paper, 2025). "Mitochondrial components, including the inner and outer membranes, were highly enriched (e.g. ATP5MC3, COX6B1 and SLC25A38; adjusted P<0.01), underscoring the role of mitochondrial reprogramming during viral infection." (PMID 40989927, 2025).
tumor (4 papers, 2014 to 2024). "Overall, the evidence in UM suggests a tumor-suppressing function for SLC25A38, which contrasts with the findings in ALL." (PMID 39795950, 2024). "Correspondingly, loss-of-function of SLC25A38 in UM cell lines, including OCM-1, MUM-2B, and 92-1, promoted cell proliferation and migration, triggered faster tumor growth, and facilitated distant metastasis in xenograft models." (PMID 39795950, 2024). "Tumors with SLC25A38 knock-out grew larger and faster in vivo, suggesting that SLC25A38 acts as a tumor suppressor in UM and its dramatic downregulation contributes to a faster rate of proliferation in cancer cells." (PMID 35411037, 2022). "Through the suppression of transcriptional coactivator for HIF signaling pathway, SLC25A38 was suited upstream of HIF signaling pathway and inhibited the production of pro-angiogenic factors, thus impeded angiogenesis and tumor progression." (PMID 35411037, 2022).
cancer (1 paper, 2022). A tumor composed of atypical neoplastic, often pleomorphic cells that invade other tissues. "Actually, we found that SLC25A38 could promote the transcription of HIF-related pathways target genes via the relief of its transcriptional coactivator CBP, which broaden our views about the relationship between SLC25A38 or glycine metabolism and HIF-related cancer progression." (PMID 35411037, 2022).
SLC25A38 also shares sentences with these, for which no sentence is quoted: uveal melanoma (2 papers); colorectal cancer (1); congenital anemia (1); Congenital hemolytic anemia (1); erythropoietic protoporphyria (1); microcytic-hypochromic anemia (1); thalassemia (1).